BRAF (B-Raf proto-oncogene, serine/threonine kinase)
Diseases named in the same sentence as BRAF in open-access papers (continued):
Sharing a sentence is not in itself a finding about the gene and the disease.
tumor (continued). "The aim of the present study was to explore the prognostic information of serum CEA and CA 19-9 in patients with mCRC, especially as related to RAS and BRAF mutation status, and with emphasis on CA 19-9 in patients with BRAF-mutant tumours." (PMID 29872151, 2018). "In 2016, a systematic review of the clinical, pathologic, and molecular characteristics of CIMP tumors showed that CIMP was associated with BRAF mutations, high MSI, female sex, right-sided tumor location, and age." (PMID 30071442, 2018). "Another prominent recent finding demonstrated that enhancement of MDSCs population in BRAF inhibitor-resistant tumour microenvironment which initially reduced after BRAF inhibitor treatment." (PMID 29455663, 2018). "In fact, the activity of BRAF inhibitors on tumor cell metabolism is reminiscent of the effects of lapachol." (PMID 29394289, 2018). "BRAF mutations are strongly associated with a CIMP that determines the silencing of various genes, including tumor suppressor genes, containing CpG islands in their promoters." (PMID 29652830, 2018). "In the present study, expression levels of CTLA-4 and PD-L1 were up-regulated in BRAF-IR group with tumor infiltrating immune cells." (PMID 30563160, 2018). "Tumor genotyping is become standard practice for CLM and clinicians often have information on the mutational status of oncogenes, including the KRAS, BRAF, PIK3CA, and NRAS oncogenes." (PMID 29774112, 2018). "This tumor-derived DNA can be extracted from plasma and used to detect BRAF proto-oncogene, KRAS, and serine/threonine kinase V600E mutations." (PMID 29728089, 2018). "Of note, combination treatment of FLT3L/poly I:C, which expands and induces the maturation and activation of CD103+ cDC1s at the tumor sites, has already been shown to enhance anti-tumor responses to BRAF and PD-L1 blockade." (PMID 30619378, 2018). "There was only 1 patients with wild-type Ras-BRAF tumor and he was treated with FOLFOXIRI regimen combined with panitumumab." (PMID 30263096, 2018). "Both Trametinib and Cobimetinib were approved in the last 5 years and are indicated for the treatment of BRAF mutant metastatic melanoma in order to avoid tumor relapse after surgical excision." (PMID 30483135, 2018). "The aim of this study was to investigate the effects of RAF and MEK concurrent inhibition on tumor growth, migration, signaling and apoptosis induction in preclinical models of non-V600 BRAF mutant tumor cell lines." (PMID 29739364, 2018). "The patients with BRAF-mutant tumours had an estimated median OS of 17 and 9 months in unadjusted analyses stratified on low and elevated serum levels of CA 19-9, respectively, and the two groups differed significantly in the tail of the Kaplan–Meier curves." (PMID 29872151, 2018). "NF1 mutations co-occurred with BRAF and RAS gene mutations in some tumours, but also frequently occurred alone." (PMID 29559732, 2018). "We also assessed the treatment response in plasma cfDNA and interestingly, changes in BRAF V600E AF compared to baseline, indicated tumor response (decrease in AF) and progression (increase in AF) at 4 and 12 weeks after commencing therapy, respectively." (PMID 30220966, 2018). "As in our cohort, LRP1 mRNA expression levels among the TCGA cohort were significantly lower in cases with right tumor location (p = 0.0003), MSI-H (p < 0.0001), BRAF mutation (p = 0.0015) CIMP-H (p < 0.0001) and low CDX2 expression (p < 0.0001)." (PMID 29507659, 2018).
tumor (continued). "In PRIME and PEAK, baseline demographics and disease characteristics were generally similar across DpR categories, although patients with DpR < 0% more commonly had BRAF mutant tumours." (PMID 29080924, 2018). "In patients with elevated serum CA 19-9 (≥35 kU/L), the median was numerically higher in those with with BRAF-mutant tumours (853 kU/L) compared to those with RAS-mutant or RAS/BRAF wild-type tumours (336 and 254 kU/L, respectively)." (PMID 29872151, 2018). "This suggests that dual activation is common in BRAF mutant tumours and accounts for why only a slight increase in power is seen between nuclear pERK and the combined pERK/p-p38 score." (PMID 29988110, 2018). "In a recent work, EREG and AREG expression has been found to have a strong inverse correlation with methylation and to be inversely associated with right-sided tumor location, CIMP-H status and BRAF mutation." (PMID 34532592, 2018). "Primary tumor site, number of metastases, ECOG performance status, BRAF status were also significantly associated with OS." (PMID 29522543, 2018). "Primary tumor tissue is used for RAS/BRAF genotyping, which is widely accepted as a basis for the treatment of mCRC because of high concordance (93–97%) between primary tumor and metastases." (PMID 29707525, 2018). "Older fibroblast produced high amounts of secreted frizzled-related protein 2 (sFRP2), a secreted protein, which was detectable in the serum of the older mice enhanced tumour angiogenesis and lung metastasis in the BRAF V 600 E model." (PMID 29492238, 2018). "Our in vitro data suggests that combination inhibition of RAF and MEK with sorafenib/AZ628 and selumetinib, respectively, should be further explored as a potential approach for inhibiting tumor growth in non-V600 BRAF mutant malignancies." (PMID 29739364, 2018). "Afterwards, the detectable free circulating BRAF in patients with PTC was mentioned as a possible determinant of tumor clinical implication." (PMID 30595827, 2018). "BRAF V600E is pro-angiogenic in several human tumour models, while VEGF has wider regulatory function beyond angiogenesis, including on immune cells." (PMID 30010756, 2018). "The aim of our study was to investigate the effect of pan-RAF inhibitors (sorafenib and AZ628) and MEK inhibitor (selumetinib) combination treatment on non-V600 BRAF mutant tumor cell lines with various BRAF activities." (PMID 29739364, 2018). "Hirata et al4 observed reduced efficacy of BRAF inhibitors in areas with high tumor stroma: in this study, tumor-stroma signaling was responsible for the reduced drug efficacy, not defects in drug access." (PMID 29985394, 2018). "The addition of macitentan to the BRAF inhibitor reduced the expression of EDNRA within the tumours, suggesting that through its affinity for EDNRA macitentan targets the AXL/EDNRA‐expressing cells." (PMID 28606996, 2017). "Almost half of the patients treated with BRAF/MEK inhibitors showed decreased tumor CD73 expression." (PMID 29202855, 2017). "Here, we found no significant connection between genetic background and sensitivity to SHR8443, which was evidenced by a mean IC50 value of 7.3 nM in KRAS/BRAF mutant tumor cells." (PMID 29296217, 2017). "They found EGFR gene deregulation in 25 out of 36 primary tumours and 29 out of 36 metastases, KRAS mutations in 16 out of 37 cancers and in 15 out of 37 metastases, and BRAF mutations in 2 out of 36 cancers and 2 out of 36 metastases." (PMID 28097409, 2017). "Our finding of a new BRAF fusion in PA further emphasis the important role of B-Raf in tumorigenesis of these tumor types." (PMID 28448514, 2017).
tumor (continued). "Mice were then treated with the BRAF inhibitor C-1 (10 mg/kg, QD, by mouth [PO]) or vehicle and tumor growth was monitored to characterize HGF-mediated rescue." (PMID 28147313, 2017). "Similar to what we observed with bosentan, BRAF inhibitor/BQ788‐treated tumours displayed increased expression of MITF and EDNRB." (PMID 28606996, 2017). "A highly significant trend for a longer survival was found in the presence of an increasing number of markers; CD8+ and FOXP3+ T cells, low tumor proliferation and BRAF wildtype status (p = 0.003)." (PMID 28851300, 2017). "In proximal colon cancer, tumor biomarkers tended to be correlated with each other, and MSI and BRAF mutation functioned as key molecular characteristics during the carcinogenesis." (PMID 28623901, 2017). "Activating mutations of the oncogenes BRAF and NRAS lead to constitutive signaling of the mitogen-activated protein kinase (MAPK) pathway and thereby enhance tumor growth and promote disease progression." (PMID 28797232, 2017). "PCR-based methods such as bead-based digital PCR in emulsions (BEAMing) and droplet-based digital PCR have been used to detect highly recurrent tumor-specific mutations in well-known driver genes such as APC, BRAF, KRAS and EGFR in plasma samples." (PMID 29156805, 2017). "cfDNA analysis showed 100% specificity and sensitivity for the BRAF V600E mutation and 98% specificity and 92% sensitivity with a concordance value of 96% for the KRAS mutation, compared with a tumor-tissue analysis." (PMID 28903450, 2017). "Again we found that while MITF was up‐regulated in BRAF inhibitor‐responding tumours, its expression was heterogeneous throughout, and strong and weak MITF‐expressing cells were detectable (Fig EV1B)." (PMID 28606996, 2017). "Intriguingly, in xenografts, the BRAF inhibitor/bosentan combination treatment led to a significant suppression of EDNRA expression within the residual tumours, which correlates with the drop in AXL expression." (PMID 28606996, 2017). "Since development of new therapy is one of the most important goals of model development, we tested the anti-tumor activities of a series of inhibitors specific to BRAF V600E or to wild-type BRAF or other types of RAF gene/pathways in vitro." (PMID 29152094, 2017). "After 20 days, tumours treated with BRAF inhibitor alone had resumed growth, whereas ERK activity was still moderately inhibited as seen by the reduced expression of DUSP6." (PMID 28606996, 2017). "BRAF inhibition also retained its therapeutic potential in BRAF-mutant tumours progressing on anti-PD-1 medication or on a sequential immunotherapy of high-dose interleukin-2 followed by ipilimumab with or without concurrent radiotherapy." (PMID 28571578, 2017). "Since coexistence of BRAF wild-type and BRAF mutant tumor cells within the same patient has important implications for clinical decisions, more sophisticated tools are needed to characterize patients’ cancers and guide their treatment." (PMID 28039443, 2017). "Intriguingly, 63% of the genes activated in fibroblasts during microtumor growth with HCT116 KRAS-driven tumor cells were also activated when cultured with HT-29 BRAF-driven tumor cells." (PMID 29245949, 2017). "We also noted associations of several cancer driver mutations in genes such as PIK3CA, BRAF, RAS family members, and FGFR3, with estimates of immune infiltrate, although these associations were often observed in limited tumor types." (PMID 28749946, 2017). "We therefore assessed EDNRA expression in the A375 xenografts and found that although it was expressed at much lower levels than EDNRB, its expression was up‐regulated in BRAF inhibitor‐treated tumours." (PMID 28606996, 2017).
tumor (continued). "Oral dosing of HL-085 (1 mg/kg, QD, 21 days) in BRAF-mutant Colo 205 and A375 xenograft models showed a high tumor growth inhibition (TGI) value (70–76%, 60–70%)." (PMID 28954413, 2017). "Firstly, our panel of tumours were evaluated for the most common KRAS (codon 12 and 13) and BRAF (V600E) mutations." (PMID 28931905, 2017). "Tissue sections were immunohistochemically stained for pERK1/2, pAKT and pp70S6K1 as markers of pathway activation, and tumor-derived DNA was analyzed for mutational status of KRAS exon 2 and BRAF exon 15 by amplicon sequencing." (PMID 28507280, 2017). "To assess the relevance of EDNRB for paracrine protection in vivo, we co‐injected A375‐T cells with A375 control cells or with A375‐shEDNRB cells into zebrafish embryos, and monitored cell death within tumours in the absence or presence of BRAF inhibitor." (PMID 28606996, 2017). "For instance, studies from our group and others have shown that oncogenic BRAF signaling in tumor cells results in the expression of immunosuppressive molecules such as VEGF in the tumor microenvironment." (PMID 28878208, 2017). "In consistent, decreased VEGF expression was also observed in tumor biopsies of patients receiving BRAF inhibitor treatment." (PMID 29156850, 2017). "This likely results from multiple factors, including tumor heterogeneity among patients, cross-resistance between BRAF and MEK, and the activation of alternative signaling pathways." (PMID 29179523, 2017). "BRAF mutation was associated with SAC morphology (P=0.042), poorer tumor differentiation (P=0.002), and CIMP-positive status (P=0.001) in colorectal MACs." (PMID 28422723, 2017). "When adjusted for age, gender, and tumor type in a multivariable Cox regression model, with the BRAF group as the reference group, the NF1 subtype still had the worst DSS (P = 0.03) and OS (P = 0.06)." (PMID 28267273, 2017). "Examples include BRAF gene amplification in MEK inhibitor treated tumor, HER2 and MET amplification in anti-EGFRab treated tumor." (PMID 28915719, 2017). "GDC-0623 has broad potency in cell-based assays, particularly in both KRAS and BRAF mutant cancer cell lines, with corresponding efficacy in xenograft tumor models." (PMID 28954413, 2017). "Thereby we identified the two common hotspot mutations BRAF V600E (c.1799 T > A;pVal600Glu; NM_004333.4) and KRAS G12D (c.35G > A;p.Gly12Asp; NM_033360.3) (8–17% of mutated reads) in 6/11 tumour samples." (PMID 29213343, 2017). "The combination of PD-1 immunotherapy with a BRAF inhibitor resulted in synergistic anti-tumor response and prominent tumor growth inhibition." (PMID 28878676, 2017). "Prevalence of BRAF and NRAS mutations, immune infiltration and PD-L1 expression in the tumor samples obtained pre-treatment were classified according to response." (PMID 29157311, 2017). "The mechanisms of drug resistance are under intensive study and include an adaptive response whereby MAPK signaling is reactivated in tumor cells despite continuous exposure to BRAF inhibitors." (PMID 29175850, 2017). "Median OS was further extended in patients with RAS WT/BRAF WT tumours receiving panitumumab (41.3 months), but remained the same as for the RAS WT population in RAS WT/BRAF WT patients receiving bevacizumab (28.9 months)." (PMID 28424871, 2017). "These activating BRAF mutations induce the constitutive downstream activation of the MEK-ERK signaling pathway, leading to tumor proliferation and survival." (PMID 28484715, 2017). "NGS-based profiling of the tumor genome identified a single nonsynonymous mutation among the many genes noted for recurrent mutations in CRC (e.g., KRAS, NRAS, BRAF, PIK3CA) and a striking focal amplification of the FGFR2 gene." (PMID 28835367, 2017). "After progression to malignancy, both BRAF and CRAF can contribute to tumour maintenance, although BRAF becomes dispensable when CRAF is expressed." (PMID 28497782, 2017).
tumor (continued). "This is of note because patients with BRAF MT mCRC have a poor prognosis and there is a small imbalance in the number of patients with BRAF MT tumours in this study (panitumumab arm n = 11; bevacizumab arm n = 3)." (PMID 28424871, 2017). "NF1 is a tumor suppressor gene encoding a direct negative regulator of RAS, which cooperates with mutated BRAF in melanomagenesis by preventing oncogene‐induced senescence." (PMID 28267273, 2017). "Taken together, our results demonstrate that only BRAF is necessary during the early stages of NRAS-induced melanomagenesis, thereby revealing a specific function for BRAF in tumour initiation that cannot be compensated by ARAF and CRAF." (PMID 28497782, 2017). "All BRAF mutations (2 patients) were homogenous in nature, where two of six (33%) patients with a KRAS mutation having evidence of intra-tumour heterogeneity." (PMID 28097409, 2017). "Given that the BRAF sequence deleted is identical to that seen in other fusion events in PA, it most likely acts as tumor driver by activation of the MAPK pathway." (PMID 29141672, 2017). "We observed similar levels of prolonged inhibition of BRAF-fusion driven tumor growth with 0.3mg/kg trametinib combined with 10mg/kg everolimus compared to 1mg/kg trametinib and 10mg/kg everolimus suggesting effectiveness of lower trametinib doses." (PMID 29156677, 2017). "Mechanisms include KRAS mutation and amplification, as well as amplification of mutant BRAF, and MEK mutations, which all converge to reactivate extracellular signal-regulated kinase (ERK) in tumor cells." (PMID 28431544, 2017). "On the other hand, there was no absolute correlation with mutational or phospho-protein markers of BRAF/MEK, RAS, or phosphoinositide 3-kinase (PI3K) activity to MEK inhibitor response in large tumor cell panels of diverse cancer types." (PMID 29296181, 2017). "A recently developed ERK1/2 inhibitor SCH77298427 showed benefits in reducing tumor growth in BRAF and MEK inhibitor- resistant models." (PMID 29180761, 2017). "Conversely, CRIS-A comprises BRAF-mutant MSI tumours but also KRAS-mutant MSS samples with MSI-like features, and overall has distinctive metabolic features." (PMID 28561063, 2017). "RAS and BRAF wild type tumours frequently respond to anti-EGFR therapy, whereas mutant tumours are refractory due to primary resistance." (PMID 28120820, 2017). "Multivariate logistic regression analysis was conducted including all of the candidate predictors (gender, location, tumor size 0–19 mm, tumor size 20–29 mm, tumor size ≥ 60 mm, mucinous component, KRAS mutation, and BRAF mutation)." (PMID 28544821, 2017). "The high concentration of BRAF V600E DNA copies (540 copies/mL plasma) is most likely related to the huge tumor burden." (PMID 28743309, 2017). "The mutation of BRAF has also increased the expression of the PD-1 and PDL-1 molecule and induces potential drug resistance with the involvement of tumor stromal cells." (PMID 28878676, 2017). "Their study demonstrated the patients harboring both BRAF and TERT mutations had an 8.5 fold greater tumor recurrence rate compared with all PTCs patients with neither mutation." (PMID 28423545, 2017). "In a paediatric patient with a recurrent BRAF V600E mutant brainstem ganglioglioma, tumour growth was blocked and vemurafenib sensitivity restored following treatment with 150 mg CQ daily for at least 30 months." (PMID 29225688, 2017).